KLK3 (kallikrein related peptidase 3)
Diseases named in the same sentence as KLK3 in open-access papers (continued):
Sharing a sentence is not in itself a finding about the gene and the disease.
prostate carcinoma (continued). "The listed genes encode for proteins with diverse biological functions, and includes KLK3/PSA which is a commonly used serum tumour marker which is clinically used for prostate cancer diagnosis and staging." (PMID 27120785, 2016). "For example, changes in glycosylation patterns have been observed for KLK3 in prostate cancer and for KLK6 ovarian cancer." (PMID 26582203, 2016). "Human kallikrein-related peptidase 2 (KLK2) is a key serine protease in semen liquefaction and prostate cancer together with KLK3/prostate-specific antigen." (PMID 26582203, 2016). "The first protein biomarkers proposed for the diagnosis of prostate cancer were serum prostatic acid phosphatase encoded by ACPP gene and prostate-specific antigen encoded by KLK3 gene." (PMID 26491211, 2015). "PROSTVAC, for example, is a prostate cancer vaccine consisting of a KLK3 recombinant vector that contains transgenes for three T-cell costimulatory molecules (TRICOM)." (PMID 26783378, 2015). "For prostate cancer, SNPs located within 10 kb the KLK3 gene were significant for summer radiation flux, winter humidity, and latitude in Bayenv." (PMID 26170196, 2015). "These genes include TP63 for bladder cancer, FGFR2 and MAP3K1 for breast cancer, HNF1B for ovarian cancer, KLK3 for prostate cancer, and CDKN2A for skin cancer." (PMID 26374197, 2015). "The successful application of KLK3 (also known as prostate-specific antigen) for prostate cancer diagnosis and prognosis has led to studies concerning KLK6 as a potential biomarker for cancers." (PMID 24669031, 2014). "The use of prostate-specific antigen, PSA (KLK3), has been debated on the base of cohort studies that show that its use in preventive screenings only marginally influences mortality from prostate cancer." (PMID 24477410, 2014). "We found that inhibition of N-linked glycosylation with tunicamycin inhibited the expression KLK3, a direct target of AR and biomarker used for blood-based test of prostate cancer." (PMID 23724116, 2013). "Due to their early discovery, KLK1-3 have been extensively studied and prostate-specific antigen (PSA), encoded by KLK3, is currently the most widely used biomarker for prostate cancer." (PMID 23894413, 2013). "KLK3 is also known as prostate cancer antigen (PSA) and is widely used as a diagnostic biomarker for prostate cancer." (PMID 23874499, 2013). "KLK3 gene encodes prostate-specific antigen (hK3), has been approved by the US FDA as the specific marker of prostate cancer, which is widely used for screening, diagnosing, determining the efficacy and assessing the prognosis of prostate cancer." (PMID 23587030, 2013). "Specifically since KLK15 is located adjacent to KLK3, and shows altered expression in prostate cancer, it is a very plausible candidate prostate cancer gene." (PMID 22132073, 2011). "For example, KIT in gastrointestinal stromal tumor (GIST; second highest weight in GIST, 0.95) and KLK2 and KLK3 in prostate cancer (the two highest weights in prostate adenocarcinoma, 0.97 and 0.95, respectively)." (PMID 21955394, 2011). "Because KLKs are secreted and readily detectable in biological fluids, they have emerged as potentially valuable biomarkers, particularly in cancer, where KLK3 (also known as prostate specific antigen) has proven to be useful for prostate cancer monitoring." (PMID 22102857, 2011). "The most recognised kallikrein is KLK3, also known as prostate-specific antigen, which is an established biomarker for detecting or monitoring prostate cancer progression and response to treatment." (PMID 18766180, 2008). "In support of this, the KLK3 gene, encoding prostate-specific antigen (PSA), is only present in primate genomes; PSA is a well known clinical marker used to monitor prostate cancer progression and response to therapy." (PMID 17257419, 2007). "Prostate specific antigen (PSA; encoded by the KLK3 gene) is the best tumour marker for prostate cancer (Diamandis, 1998." (PMID 11986781, 2002).
prostate carcinoma (continued). "However, significant changes in the N-glycosylation patterns were observed for Asn61 of KLK3/PSA in prostate cancer, including an additional N-glycosylation site in the Asp95Asn variant, and for Asn132 of KLK6 in ovarian cancer." (PMID 41516101, 2025). "Following this, the expression levels of apoptosis-related genes (BAX, Bcl-2), an angiogenesis gene (VEGF-C), a gene associated with progression and development (HIF-1α), genes involved in the EMT pathway (SNAIL and E-Cadherin), and a prostate cancer marker (KLK3) were evaluated using Real-Time PCR." (PMID 40388455, 2025). "Furthermore, all medication groups significantly reduced the expression of the prostate cancer biomarker known as KLK3 (p < 0.05)." (PMID 40388455, 2025). "Looking specifically at AR-associated gene expression in our treatment-naïve primary prostate cancer samples, our AIPC cohort demonstrates significantly lower expression of AR, FOXA1, TMPRSS2, KLK3, AZGP1, and several other AR-associated genes when compared with the non-AIPC cohort." (PMID 39859392, 2025). "Likewise, for C61 (prostate cancer), the AUC improved from 0.54 to 0.76 due to the addition of the known prostate cancer antigen (KLK3)." (PMID 39261665, 2024). "Notably, a class of ncRNAs known as androgen-inducible eRNAs facilitates androgen-induced prostate-specific antigen [PSA (KLK3)] gene expression in human prostate cancer cell lines." (PMID 37025180, 2023). "The non-synonymous KLK3 SNP, rs17632542 (c.536T>C; Ile163Thr-substitution in PSA) is associated with reduced prostate cancer risk, however, the functional relevance is unknown." (PMID 37034758, 2023). "In addition, tissue-specific highly expressed eRNAs, such as CCAT1 in colorectal cancer and androgen receptor (AR)-induced Kallikrein-related peptidase 3 (KLK3) eRNA (KLK3e) in prostate cancer, are considered new targets for treating various cancers." (PMID 35039581, 2022). "Similarly, in human prostate cancer, an adjacent eRNA of kallikrein‐related peptidase 3 (KLK3) can regulate target genes expression in trans." (PMID 35851988, 2022). "Furthermore, most studies in the context of localised prostate cancer focus on KLK3 gene expression in CTCs." (PMID 35493092, 2022). "Although not common, the VEGFC/KLK3 SNP–SNP interaction pair rs174776/rs3775202 was highly significantly associated with prostate cancer aggressiveness." (PMID 34948344, 2021). "For example, in prostate cancer, Kallikrein-related peptidase 3 eRNA (KLK3e), an eRNA produced by KLK3’s upstream enhancers, can selectively enhance the androgen receptor (AR)-dependent gene expression, resulting in a positive effect on prostate cancer cell proliferation." (PMID 33996902, 2021). "Thus, it is relevant to consider the regulation of VEGFs in the context of prostate cancer to further understand the role of KLK3 activation of VEGF-C and -D." (PMID 34948344, 2021). "Thus, it appears that KLK3 and VEGF-C, which KLK3 is able to activate, are, at least partially, similarly regulated by androgens in prostate cancer." (PMID 34948344, 2021). "Providing that KLK3 has antiangiogenic activity in prostate cancer, the slow growth of prostate cancer could be related to the antiangiogenic activity of KLK3." (PMID 34948344, 2021). "In our study, KLK2, KLK3, and KLK4 were identified as gene signatures for prostate cancer; KLK3 is a prostate-specific antigen that is a gold-standard clinical biomarker widely employed in the diagnosis and monitoring of prostate cancer; KLK2 showed promise as prostate cancer biomarker, as well." (PMID 32850691, 2020). "Additionally, the development of selective KLK3 inhibitors was focused for targeted treatment of prostate cancer." (PMID 32529252, 2020). "Similar to KLK3, also Kallikrein related peptidase 2 (KLK2) functions in hydrolyzing seminogelins and is regulated by androgen receptor, upregulated in prostate tumor cells, and recognized as potential prognostic maker for prostate cancer risk." (PMID 33114768, 2020).
prostate carcinoma (continued). "The Kallikrein 3 (KLK3) gene is identified as a biomarker of prostate cancer by many researchers." (PMID 30838019, 2019). "VEGF-C expression, which overlaps in the prostate with KLK3 expression, is similarly controversial, with some studies supporting and others refuting its predictive ability for prostate cancer progression." (PMID 31099754, 2019). "KLK3 is located on chromosome 19 and found to be over expressed of in men's prostate cancer cells." (PMID 30838019, 2019). "Kallikrein-related peptidase 3 (KLK3) or prostate-specific antigen (PSA) is widely known as a prostate cancer marker, which may also participate in prostate cancer development." (PMID 31099754, 2019). "We have hypothesized that KLK3 may facilitate early development of prostate cancer, but at later stages slow down cancer growth." (PMID 31099754, 2019). "Alongside the microfluidic experiments, RT-qPCR was performed for each biopsy to assess the presence of prostate cancer cells and several prostate cancer biomarkers: androgen receptors (ARs), prostate-specific androgen (KLK3) and alpha-methyl-acyl-CoA racemase (AMACR)." (PMID 30279484, 2018). "The eight proteins highlighted in this study (KLK3, SORD, SPON2, IMPDH2, ACTN4, ATP1B1, HSPB1, and KHDRBS1) represent a signature associated with AR modulation during the transition from androgen-dependent to castration-resistant prostate cancers." (PMID 29966326, 2018). "Circulating biomarkers in body fluids present advantages in the clinical diagnostic practice for the easy access as in the case of the prostate antigen (PSA, KLK3) is widely used to screen for prostate cancer while troponin (TNNT2) is a valid marker for myocardial infarction." (PMID 30920517, 2017). "Notably, one group of genes with very strong negative correlations (≤-0.9) to radiomic features were found to be associated with the AR signaling genes: KLK2, KLK3, HOMER2, BMPR1B, or belong to validated prostate cancer classifiers: CHRNA2, MT1H, DPP4, MYBPC1." (PMID 27438142, 2016). "The introduction of testing for prostate-specific antigen (PSA), a member of the fifteen-gene family of kallikrein-related peptidases and also known as kallikrein-related peptidase 3 (KLK3), in blood has revolutionized both the detection and management of prostate cancer." (PMID 24809052, 2014). "A list of candidate biomarkers was chosen according to a set of criteria, highlighting KLK6, a protein that belongs to the 15-member KLK family in which KLK3 (also known as prostate-specific antigen) is the most useful marker for the early detection of prostate cancer." (PMID 24669031, 2014). "It should be noted that the gene GSTP1 was in an association with ferritin H gene, gene LHB was significantly with testosterone and estradiol levels and special CYP3A/KLK3 genotypes increased metastatic disease while the expression of CYP3A in prostate cancer was regulated by androgen." (PMID 24146788, 2013). "KLK3 or prostate specific antigen is secreted from the prostate secretion, and may play a role as a biomarker in prostate cancer." (PMID 24004880, 2013). "Receiver operator characteristic (ROC) curves were used to determine whether coding and non-coding prostate cancer biomarkers could differentiate BxPos (n=47) from BxNeg patients (n=39) using exoRNA standardised to the prostate marker KLK3." (PMID 26082317, 2013). "In addition to prostate cancer, breast, colon, ovarian, liver and kidney tumors can also produce KLK3." (PMID 22496748, 2012). "We did not observe such differences, however, suggesting that the KLK3-prostate cancer association is not mediated by altered PSA levels." (PMID 21390317, 2011). "Uncontrolled proteolytic activities of KLKs are associated with disease states including cancer, inflammation, and neurodegeneration, and they are overexpressed in various malignancies; for example, KLK3 expression is currently used as a marker for prostate cancer." (PMID 21647431, 2011).
prostate carcinoma (continued). "As been shown for prostate-specific antigen (PSA/KLK3) in prostate cancer, these may represent potential novel biomarkers for ovarian carcinoma." (PMID 19707197, 2009). "Moreover, KLK3, also known as prostate-specific antigen, is of great clinical value as a serological marker in prostate cancer." (PMID 18854834, 2008). "Hence, we aimed to assess the combined impact of SeNPs and Flutamide on the growth and programmed cell death, as well as the expression of various genes such as SNAIL, KLK3, E-cadherin, and apoptotic genes in three types of prostate cancer cells: LNCaP, PC3, and DU145." (PMID 40388455, 2025). "Different strategies have been developed for non-invasive diagnosis of prostate cancer including nanotechnology and liquid biopsies to identify circulating tumor cells, circulating nucleic acids, or exosomes, as well as other reliable biomarkers such as KLK3/prostate-specific antigen tests." (PMID 35317831, 2022). "Thus, the clinical studies may be interpreted to support a dual role for KLK3 in prostate cancer, i.e., KLK3 may favor tumor development at early stages of prostate cancer and later inhibit tumor growth by its antiangiogenic activity." (PMID 34948344, 2021). "Also, tissue-specific genes with protein products entering the bloodstream may find applications as biomarkers (KLK3 in prostate cancer) or replacement therapies (e.g., insulin in type 1 diabetes)." (PMID 31076736, 2019). "Besides, KLK3 has been found to be related to prostate cancer in several previous studies." (PMID 29142286, 2017). "IHC assessed key prostate cancer markers (AR, AMACR, KLK3, PTEN, NKX3-1, VIM), while WES compared somatic alterations in PGCA, adjacent adenocarcinoma, and stromal tissue." (PMID 40873563, 2025). "In this regard, various new biomarkers are being tested for PSMA-negative prostate cancer, most notable novel biomarkers being tested are CD46, human KLK3, and VE-cadherin." (PMID 38773983, 2024). "Well-known prostate cancer signatures, including KLK3, a serine protease used as a serum marker in prostate cancer screening and disease monitoring, and PRAC, a highly expressed gene in prostate cancer, have been selected by 7 and 3 studies, respectively." (PMID 38028533, 2023). "Our work demonstrated this in two prostate cancer cell lines, in which SHBG-bound T was internalized, resulting in KLK3 induction." (PMID 36875158, 2023). "The reported ABPs specific for KLK2, KLK3 and KLK14 allowed their simultaneous orthogonal analysis in prostate cancer cell lines." (PMID 35631563, 2022). "KLK3 is expressed in BLCA, BRCA, LIHC, and LUAD, and the gene is highly expressed in cancers such as prostate cancer and breast cancer." (PMID 36016607, 2022). "In particular, because of the restricted expression in prostate, KLK3, also known as a prostate-specific antigen (PSA), has been widely employed as a clinical biomarker for prostate cancer." (PMID 35222418, 2022). "We called 125,569 peaks and identified differentially accessible peaks around the promoter regions of several key genes in prostate cancer such as MYC and KLK3." (PMID 34911933, 2021). "The related kallikrein gene KLK2 had expression that was highly correlated with KLK3, as did TMPRSS2, one of the genes involved in the TMPRSS2:ERG translocation that is common in prostate cancer." (PMID 33303959, 2020). "Of note, in prostate cancer, KLK-3, which is also commonly known as the prostate-specific antigen (PSA), has been used as a biomarker for prostate cancer screening, although its diagnostic value still remains controversial." (PMID 32948029, 2020). "For example, among the top 10 up-regulated genes, KLK3 and KLK2, are highly enriched in prostate cancer, which are taken as effective biomarkers for diagnose and prognostic monitoring of prostate cancer." (PMID 33604283, 2020).
prostate carcinoma (continued). "Kallikrein related peptidase 3 (KLK3), also referred to as prostate specific antigen (PSA), is a well-known biomarker in blood for prostate cancer, secreted by prostate epithelial cells." (PMID 33114768, 2020). "From the literature data, we find that KLK3 and NPEPPS have been studied together in 52 articles in prostate cancer research in genetics among Finnish researchers." (PMID 30838019, 2019). "KLK3, better known as prostate-specific antigen (PSA), is widely used in detecting and monitoring prostate cancer progression, but other kallikreins will likely prove useful to monitor a variety of cancers." (PMID 30925705, 2019). "Further, the increased expression of AR, KLK3 and AMACR in Patient 1 and 2 suggests the presence of prostate cancer cells within the mixed biopsy population." (PMID 30279484, 2018). "KLK3, or prostate-specific antigen (PSA), is the most recognized member of the family with its ubiquitous use in prostate cancer screening." (PMID 29707153, 2018). "The KLK3 gene produces prostate specific antigen (PSA), a widely used biomarker for prostate cancer." (PMID 26170196, 2015). "Other genes identified as highly enriched in prostate cancer were TGM4, KLK2 and KLK4, the latter kalekrein-related proteins belonging to the same family as PSA (KLK3)." (PMID 26237329, 2015). "The most well-known kallikrein is prostate-specific antigen (KLK3), which is used clinically to diagnose human prostate cancer." (PMID 24708840, 2014). "PSA/KLK3, a member of KLK gene family, is a well established and clinically-used biomarker for prostate cancer." (PMID 24043563, 2014). "RNA from a dilution series of prostate cancer lines C4-2 and PC3 was prepared, and hybridized to a probe library of six selected genes: KLK3, CD90/THY1, AGR2, HPN, PCA3, UPK3A." (PMID 23029164, 2012). "KLK3 (also known as prostate-specific antigen, PSA) is a kallikrein-like serine protease that is a widely used biomarker for prostate cancer." (PMID 22496748, 2012). "Prostate cancer is primarily detected using serum levels of kallikrein-related peptidase 3 (KLK3, prostate-specific antigen, PSA), which is the established biomarker for diagnosis and prognosis." (PMID 21556330, 2011). "KLK3, also known as prostate-specific antigen (PSA), is the main tumor marker for prostate cancer and has been used clinically for 15 years." (PMID 19832994, 2009). "Five of these top seven genes namely, MYLK, KLK2, KLK3, LTF and TGM4 had already been specifically related to prostate carcinoma." (PMID 19055846, 2008). "Considering the link between HSPs and AR activity, we next investigated the impact of NXP800 on AR signaling, demonstrating a decrease in AR-FL and AR-V7 protein expression, and also in expression of AR-responsive genes (KLK2, KLK3, TMPRSS2, and FKBP5), across all three prostate cancer cell lines." (PMID 39787247, 2025). "Interestingly, KLK3 (prostate-specific antigen, PSA) is a well-established biomarker in prostate cancer; however, its role in BC remains less well-documented." (PMID 40427030, 2025). "Dihydrotestosterone (DHT) treatment significantly increased PEX10 expression at the mRNA and protein levels in prostate cancer cells, including C4-2 and LNCaP cells, while enzalutamide treatment decreased PEX10 expression, which is consistent with the changes in KLK3 and our previous conclusions." (PMID 39097593, 2024). "The expression of KLK3e is correlated with KLK3 and KLK2 in prostate cancer." (PMID 35170113, 2022). "This supports the potential role of KLK3 as a VEGF-C activator in prostate cancer and that they may act in a concerted fashion to drive prostate cancer progression." (PMID 34948344, 2021). "As reported, LNCaP, C4-2, 22RV1, and VCaP cells exhibited robust AR activity by means of KLK3 expression, whereas PC3 and DU145 (AR-negative prostate cancer cells) or RWPE1, PWR1E, and BPH1 cells (benign prostate immortalized cells) exhibited low activity of the nuclear receptor." (PMID 34503116, 2021).